ENPP1 (ectonucleotide pyrophosphatase/phosphodiesterase 1)
Description:
Nucleotide pyrophosphatase that generates diphosphate (PPi) and functions in bone mineralization and soft tissue calcification by regulating pyrophosphate levels (By similarity). PPi inhibits bone mineralization and soft tissue calcification by binding to nascent hydroxyapatite crystals, thereby preventing further growth of these crystals. Preferentially hydrolyzes ATP, but can also hydrolyze other nucleoside 5' triphosphates such as GTP, CTP and UTP to their corresponding monophosphates with release of pyrophosphate, as well as diadenosine polyphosphates, and also 3',5'-cAMP to AMP. May also be involved in the regulation of the availability of nucleotide sugars in the endoplasmic reticulum and Golgi, and the regulation of purinergic signaling. Inhibits ectopic joint calcification and maintains articular chondrocytes by repressing hedgehog signaling; it is however unclear whether hedgehog inhibition is direct or indirect (By similarity). Appears to modulate insulin sensitivity and function. Also involved in melanogenesis. Also able to hydrolyze 2',3'-cGAMP (cyclic GMP-AMP), a second messenger that activates TMEM173/STING and triggers type-I interferon production. 2',3'-cGAMP degradation takes place in the lumen or extracellular space, and not in the cytosol where it is produced; the role of 2',3'-cGAMP hydrolysis is therefore unclear. Not able to hydrolyze the 2',3'-cGAMP linkage isomer 3'-3'-cGAMP.
Synonyms: M6S1; NPPS; PDNP1; PC-1; PCA1; ARHR2; COLED; NPP1
Tractability: Small molecule: a structure with a bound ligand is known; a high-quality ligand is known. Antibody: UniProt places it where antibodies can reach, with high confidence; its Gene Ontology location is reachable by antibodies, with high confidence; UniProt predicts a signal peptide or a membrane-spanning region. PROTAC: its protein half-life has been measured; a small molecule that binds it is known.
Target class: Enzyme
Gene: Protein-coding gene on chromosome 6 (131,807,993 to 131,895,155, forward strand). Ensembl gene ENSG00000197594.
Subcellular location: Cell membrane (Ectonucleotide pyrophosphatase/phosphodiesterase family member 1); Basolateral cell membrane; Secreted (Ectonucleotide pyrophosphatase/phosphodiesterase family member 1, secreted form)
Pathways (Reactome):
Metabolism: Vitamin B2 (riboflavin) metabolism; Vitamin B5 (pantothenate) metabolism
Gene Ontology:
Molecular function: 3',5'-cyclic-AMP phosphodiesterase activity; ATP binding; ATP diphosphatase activity; cyclic-GMP-AMP hydrolase activity; dinucleotide phosphatase activity; exonuclease activity; insulin receptor binding; nucleoside triphosphate diphosphatase activity; phosphatase activity; phosphodiesterase I activity; protein binding; protein homodimerization activity; UTP diphosphatase activity; 3'-phosphoadenosine 5'-phosphosulfate binding; calcium ion binding; GTP diphosphatase activity; zinc ion binding; hydrolase activity; metal ion binding; nucleic acid binding; polysaccharide binding; scavenger receptor activity
Biological process: 3'-phosphoadenosine 5'-phosphosulfate metabolic process; ATP metabolic process; bone mineralization; cellular response to insulin stimulus; gene expression; generation of precursor metabolites and energy; inorganic diphosphate transport; intracellular phosphate ion homeostasis; melanocyte differentiation; negative regulation of cell growth; negative regulation of D-glucose import; negative regulation of fat cell differentiation; negative regulation of glycogen biosynthetic process; negative regulation of insulin receptor signaling pathway; nucleic acid metabolic process; nucleoside triphosphate catabolic process; phosphate ion homeostasis; phosphate-containing compound metabolic process; response to ATP; negative regulation of bone mineralization; regulation of bone mineralization; animal organ development; immune response; vesicle-mediated transport
Cellular component: basolateral plasma membrane; cell surface; extracellular region; lysosomal membrane; plasma membrane; membrane
Genetic constraint (gnomAD): Loss-of-function variants: 33 observed, 60.56 expected, observed/expected ratio (o/e) 0.54, 90% interval 0.41 to 0.73. The upper end of that interval is the gene's LOEUF score, 0.73, which puts it in group 2 of 6, group 1 being the genes least tolerant of losing a copy. Missense variants: 662 observed, 752.77 expected, observed/expected ratio (o/e) 0.88, 90% interval 0.82 to 0.94. Synonymous variants: 263 observed, 264.37 expected, observed/expected ratio (o/e) 0.99, 90% interval 0.9 to 1.1.
Gene-disease validity (ClinGen):
ClinGen rates the evidence that ENPP1 causes each of these diseases.
arterial calcification, generalized, of infancy, 1 (autosomal recessive): Definitive.
hypopigmentation-punctate palmoplantar keratoderma syndrome (autosomal dominant): Limited.
Homologues: Orthologues: chimpanzee ENPP1 (99% identical), macaque ENPP1 (98% identical), pig ENPP1 (89% identical), rabbit ENPP1 (87% identical), dog ENPP1 (86% identical), mouse Enpp1 (78% identical), rat Enpp1 (78% identical), guinea pig ENPP1 (77% identical), tropical clawed frog enpp1 (58% identical), zebrafish enpp1 (51% identical), Caenorhabditis elegans enpp-1 (22% identical), Caenorhabditis elegans C27A7.3 (22% identical), and 1 more. Paralogues in human: ENPP3 (50% identical), ENPP2 (41% identical), ENPP4 (17% identical), ENPP5 (16% identical), ENPP6 (15% identical), ENPP7 (15% identical).
Diseases named in the same sentence as ENPP1 in open-access papers:
ENPP1 is named in the same sentence as 180 diseases in open-access papers, as found by Europe PMC text mining. Sharing a sentence is not in itself a finding about the gene and the disease. The quoted sentences say what the papers report.
Insulin resistance (52 papers, 2007 to 2025). Increased resistance towards insulin, that is, diminished effectiveness of insulin in reducing blood glucose levels. "Ectonucleotide pyrophosphatase/phosphodiesterase family member 1 (ENPP1) was associated with insulin resistance by inhibiting the activity of insulin receptor (IR) and concomitantly preventing downstream signaling." (PMID 38122899, 2024). "Specific mutations in ENPP1 are associated with increased insulin resistance in humans and show diversity between ethnic groups." (PMID 39184263, 2023). "The enzyme ectonucleotide pyrophosphatase phosphodiesterase 1 (ENPP1) is recognised as a pathogenic factor predisposing to insulin resistance in humans by allosterically modulating the insulin receptor and negatively impacting insulin pathways." (PMID 39184263, 2023). "Previous studies have revealed that ENPP1 directly interacts with IR and inhibits insulin signaling, and the binding of Gal-3 to IR causes insulin resistance." (PMID 37067034, 2023). "Ectonucleotide pyrophosphatase/phosphodiesterase 1 ENPP1/PC1 variants have been shown associated with insulin resistance leading to increased risk for T2D." (PMID 35763080, 2022). "The association of the K121Q polymorphism of the ENPP1 gene with obesity and insulin resistance was investigated in various populations." (PMID 34208364, 2021). "There were discrepancies regarding the association of the K121Q polymorphism of the ENPP1 gene with obesity and insulin resistance in various populations." (PMID 34208364, 2021). "We performed regression logistic analysis to calculate the OR of obesity and insulin resistance associated with the K121Q SNP of the ENPP1 gene." (PMID 34208364, 2021). "ENPP1 has been suggested to play a role in pathophysiological changes associated with insulin resistance such as hyperglycaemia through elevated hepatic gluconeogenesis." (PMID 33154392, 2020). "Genetic variations and polymorphisms of ENPP1 have been associated with insulin resistance in human subjects." (PMID 29513794, 2018). "As it has been reviewed, elevated ENPP1 protein level and enzymatic activity are associated with insulin resistance and type 2 diabetes." (PMID 29513794, 2018). "The role of Enpp1 in β-cells remains elusive, although its overexpression in plasma has been associated with insulin resistance and T2D, and the in vitro studies indicate that it affects both β-cell function and survival." (PMID 26335571, 2015). "Recent studies have demonstrated that ENPP1 affects both the function and survival of pancreatic beta cells, thus representing a strong pathogenic factor predisposing to insulin resistance, defective insulin secretion, and impaired glucose metabolism." (PMID 26302420, 2015). "Variants of ENPP1 in human GWAS studies have been associated with obesity, type 2 diabetes and a primary role in insulin resistance." (PMID 23826075, 2013). "Evidence can be found that the variants of ENPP1 were associated with insulin resistance (IR)/atherogenic phenotypes, including earlier onset of 2DM and myocardial infarction." (PMID 22697793, 2012). "Variation in ENPP1 has previously been associated with obesity, type 2 diabetes and insulin resistance." (PMID 21283750, 2011). "According to this view, ENPP1 over-expression in liver and muscle, two main tissues involved in insulin-mediated regulation of glucose and lipid metabolism, determines insulin resistance and susceptibility to type 2 diabetes." (PMID 17849011, 2007). "For example we have shown that South Asians have a relative increase in a polymorphism of ENPP1/PC-1 that has been reported to be associated with increased insulin resistance and predisposition to type 2 diabetes." (PMID 17726542, 2007). "Additionally, ENPP1 has also been linked to insulin resistance, type 2 diabetes, Cole disease, cancer metastasis, and osteoarthritis, highlighting its functional significance and the heterogeneity of ENPP1 mutation-related phenotypes." (PMID 40535334, 2025).
Insulin resistance (continued). "Additionally, ENPP1 blocks insulin signaling, and insulin resistance is linked to an ENPP1 polymorphism." (PMID 36234712, 2022). "In human studies, the presence of ENPP1 rs1044498*C polymorphism in Caucasian populations is associated with insulin resistance when assessed by the homeostasis model assessment (HOMA-IR), accompanied by elevated HbA1c, fasting insulin, and fasting plasma glucose levels." (PMID 35055468, 2022). "We investigated the association of ENPP1 SNP K121Q (rs1044498) with insulin resistance and ADIPOQ SNP + 267G > T (rs1501299) with circulating adiponectin levels in a case–control study involving 55 obese and 55 lean Javanese people residing in Yogyakarta, Indonesia." (PMID 34208364, 2021). "In addition, insulin resistance, a fundamental starting point for most metabolic diseases, has been linked with ENPP1 mutations in several studies." (PMID 31752288, 2019). "One protein that has been implicated to cause insulin resistance is ectonucleotide pyrophosphatase/phosphodiesterase 1 (ENPP1) or plasma cell membrane glycoprotein 1, which is thought to hydrolyze ATP to generate inorganic pyrophosphate (PPi) plus AMP or inorganic phosphate (Pi) plus ADP." (PMID 29513794, 2018). "Several genes have been mapped to the 6q region including the TCBA1 gene, which is associated with developmental delay and recurrent infections, the ENPP1 gene, associated with insulin resistance and susceptibility to obesity and the BMIQ3 gene, associated with body mass index (BMI)." (PMID 26110021, 2015). "Given that elevated NPP1 is associated with insulin resistance, we hypothesized that ENPP1 gene deletion would promote improved glucose homeostasis in the context of obesity-associated diabetes." (PMID 25368121, 2014). "In addition to T2D, the ENPP1/PC-1 Q121 allele has also been reported to influence the risk of obesity, a condition characterized by insulin resistance." (PMID 23762820, 2013). "Furthersupport to the notion that ENPP1 may play a role on human insulin resistance derivesfrom studies on the ENPP1 K121Q polymorphism, which has drawn someattention as a genetic determinant of human insulin resistance." (PMID 21573217, 2011). "ENPP1 K121Q could be an important determinant of genetic susceptibility to insulin resistance and may provide a useful clinical marker and a therapeutic target for insulin resistance, type 2 diabetes and cardiovascular disease." (PMID 17849011, 2007). "In addition, we have recently shown an interaction between ENPP1 121Q variant and BMI in humans in predicting insulin resistance and type 2 diabetes." (PMID 17849011, 2007). "The variants of genes like PPARG, ADIPOQ, and ENPP1 which act at the level of insulin resistance have been shown to increase the risk of T2DM only in obese populations and hence it has been suggested that T2DM risk contribution of gene polymorphism may be modulated by obesity status." (PMID 26491214, 2015). "In an effort to clarify whether increased expression of ENPP1 is associated with insulin resistance and diabetes in LMNA K542N homozygotes, oral glucose tolerance testing (oGTT) was performed on both healthy parents and two affected children (at age 10 and 20 years)." (PMID 21738662, 2011). "Interestingly, the variants in PPARG, ADIPOQ, and ENPP1, which elevate risk in obese populations, have been categorized as acting on insulin resistance while the TCF7L2 variant elevating risk in lean populations has been categorized as acting on insulin secretion." (PMID 18498634, 2008). "It was observed that the liver Enpp1 expression were lower in MAFLD patients and MAFLD mouse models, whereas the Enpp1 deficient MAFLD mice exhibited enhanced obesity, insulin resistance and hepatic steatosis." (PMID 39972484, 2025). "Enpp1, which is known to inhibit insulin signaling and potentially leads to insulin resistance, was shown as a prime target of G4 repression." (PMID 40913227, 2025).
Insulin resistance (continued). "Knocking out Enpp1 in the liver of mice aggravated obesity, insulin resistance and hepatic steatosis, and these effects were reversed by liver-specific Enpp1 overexpression." (PMID 39972484, 2025). "Ectonucleotide pyrophosphatase/phosphodiesterase 1 (Enpp1) has been found to be related to insulin resistance and lipid accumulation." (PMID 39972484, 2025). "Overexpression of ENPP1 in mice leads to insulin resistance and MGAT2 deficiency reduces lipid absorption and insulin resistance." (PMID 36858953, 2023). "In mouse models, ablation of Enpp1 results in profound resistance to obesity and insulin resistance following a high-fat diet challenge." (PMID 39184263, 2023). "The ENPP1 expression in adipose tissue is increased in obese patients with insulin resistance, and ENPP1 is also considered both a biomarker and a novel potential therapeutic target to improve adipose tissue function and systemic glucose metabolism." (PMID 34289582, 2022). "The protein level of ENPP1 was increased in the adipose tissue of individuals suffering from insulin resistance." (PMID 34208364, 2021). "ENPP1 is known to be involved in insulin resistance by inhibiting the interaction between insulin and the receptor at the level of the alpha subunit, resulting in decreased downstream insulin signaling activation." (PMID 32884006, 2020). "Given the fact that ENPP1 is detected in the liver and its hepatic over-expression leads to insulin resistance, we aimed to investigate the regulation of hepatic Enpp1 expression." (PMID 29513794, 2018). "Increased ENPP1 expression in the liver of ENPP1 transgenic mice correlates with insulin resistance and glucose intolerance." (PMID 29259245, 2017). "Transgenic mice overexpressing human ENPP1 in muscle and liver tissue exhibited elevation in glucose and insulin levels compared to wild-type, conveying that ENPP1 plays a role in insulin resistance and hyperglycemia." (PMID 25825681, 2015). "Despite the role of ENPP1 in insulin resistance, data on its role in human liver insulin resistance is lacking." (PMID 25539584, 2014). "Ectonucleotide pyrophosphatase/phosphodiesterase-1 (NPP1) controls bone mineralization through the generation of pyrophosphate, and levels of NPP1 are elevated both in dermal fibroblast cultures and muscle of individuals with insulin resistance." (PMID 25368121, 2014). "ENPP1 mutations cause autosomal recessive hypophosphatemic rickets (ARHR2; MIM 173335) in mice and man and over expression induces hyperglycemia, insulin resistance and diabetes." (PMID 24839967, 2014). "Increased expression of Enpp1 or its overactivity is correlated with insulin resistance, through direct effects in the insulin signaling pathway." (PMID 23826075, 2013). "The ancestral alleles of these SNPs have previously been associated with the nutrition-related diseases hypertension (AGT and CYP3A7) and insulin resistance (ENPP1)." (PMID 23036011, 2012). "The ancestral alleles of these SNPs have previously been associated with nutrition-related diseases hypertension (AGT and CYP3A7) and insulin resistance (ENPP1)." (PMID 23036011, 2012). "Ectonucleotide pyrophosphatase phosphodiesterase 1 (ENPP1) is a class IItransmembrane glycoprotein, which inhibits insulin receptor (IR) signaling and whichhas been, therefore, proposed as a candidate for insulin resistance." (PMID 21573217, 2011). "Conversely, insulin resistance associated genetic variants of PPARG, ADIPOQ and ENPP1 were found to be only associated in obese subjects." (PMID 18498634, 2008). "In summary, the results of our studies support a role of increased ENPP1 expression in the pathogenesis of insulin resistance in humans." (PMID 17849011, 2007). "This seems to be of importance in light of the high expression of ENPP1 in human adipose tissue and in light of the role that adipose tissue function plays in the pathogenesis of systemic insulin resistance and type 2 diabetes." (PMID 17849011, 2007).